EPCAM (epithelial cell adhesion molecule)
Diseases named in the same sentence as EPCAM in open-access papers (continued):
Sharing a sentence is not in itself a finding about the gene and the disease.
tumor (continued). "As one of the first tumor-related antigens, epithelial cell adhesion/activating molecule (EpCAM/CD326) has been reported highly overexpressed in primary and metastatic breast cancer, leading to poor prognosis." (PMID 37875600, 2023). "Tumour cells were recovered, stained for cytokeratins, EpCAM, CD45, and with a Hoechst dye, and detached from beads leading to recovery rates of 45.2% for SK-BR-3 and 44.0% for T-47D cells." (PMID 36823365, 2023). "The study aims to see if circulating tumor cells (EpCAM or CD52 as marker) can be removed out of the blood with the help of these particles for the aim of leukemia diagnosis." (PMID 38053150, 2023). "The overexpression of RHOJ in EPCAM+ tumour cells slightly decreased the growth of cells in vitro and did not affect the expression of EMT or epithelial markers." (PMID 36949199, 2023). "Low passage cytokeratin+, aneuploid MPE tumor cells evidenced a high degree of EMT as documented by surface expression of CD90, CD44, and loss of surface expression of EpCAM." (PMID 37063842, 2023). "Recent studies suggest that cancer-derived exosomes have been found to be involved in remodeling the tumor microenvironment, promoting angiogenesis, and modulating the immune system and that some exosomes can secrete epithelial cell adhesion molecules (EpCAM)." (PMID 37370845, 2023). "Catumaxomab (anti-EpCAM × anti-CD3) is a bispecific monoclonal antibody that binds to both EpCAM (on tumor cells) and CD3 (on T cells)." (PMID 36899854, 2023). "The treatment by low doses of these drugs moderately reduced F-actin and cell stiffness and significantly increased the formation and growth of tumor spheroids and the EpCAM+ subpopulation." (PMID 37746658, 2023). "Subsequent immunofluorescent imaging showed that EpCAM-positive tumor cells were present in addition to regions of embedded CD45-positive immune cells." (PMID 37627156, 2023). "Since we used CD49f together with EpCAM to discriminate tumor cells in our WB1P and WB1P-Myc models, we potentially ignored tumor-cell derived CAFs in our analysis." (PMID 36635273, 2023). "Since the discovery of the epithelial cell adhesion molecule (EpCAM) as a tumor marker in 1979, many studies have investigated its structure and function." (PMID 37154925, 2023). "Further, the total number of CD133+ stem cells within the GFP+EpCAM+ tumor fraction was reduced by up to 100-fold in shSmarcd3-treated tumors relative to shControl (right)." (PMID 36653361, 2023). "They found that the probability of tumor progression was significantly lower in patients who received high doses of adecatumumab, and who expressed high levels of EpCAM." (PMID 36899854, 2023). "Patients with EpCAM-positive alpha-fetoprotein (AFP)-positive HCC are usually young but have advanced tumor-node-metastasis (TNM) stages." (PMID 36674932, 2023). "EpCAM and Wnt/β-catenin pathway are functionally connected and share a significant role in tumor progression and increasing the stemness properties of hepatic CSCs." (PMID 37941056, 2023). "KIT, CD34, THY1, and EPCAM were expressed in large vessel structures and tumor capsules from patients #4001 and #3559." (PMID 37932266, 2023). "The tumor/stromal cells included one CD56+fibroblast population and nine CD45−CD56−cell populations, which were distinguished by the expression of the three select tumor markers, namely, EpCAM, FOLR1, and CD24." (PMID 37894472, 2023). "They defined the tumor cells as EpCAM+ CD45-, the stromal cells as EpCAM- CD45-, and the immune cells as EpCAM-CD45+." (PMID 36672620, 2023). "In contrast, solid metastatic organoids showed a reduction in EpCAM and Cldn7 levels compared to glandular primary tumor organoids." (PMID 36828915, 2023). "GSE39396 dataset contains cell data for the following cell populations EPCAM(+) tumor epithelial cells, FAP(+) CAFs, CD45(+) leucocytes, and CD31(+) endothelial cells." (PMID 37964075, 2023).
tumor (continued). "EpCam is a key molecule for homophilic cell to cell adhesion and is involved in tumor cell proliferation and adhesion via cadherin." (PMID 37370706, 2023). "In combination with EpCAM, we stained tumour specimens for CD24 as a second marker of plastic EMT CSCs, and Vimentin as a mesenchymal marker to identify cells that have undergone EMT." (PMID 37975646, 2023). "The distribution of the chromosomal CNA patterns found on the CK/EpCAM CTCs in our study were similar to the ones from HGSOC tumours reported by TCGA23 and CTCs from HGSOC patients." (PMID 36781954, 2023). "By univariate and multivariate Cox regression analysis, we confirmed previous studies indicating serum AFP levels ≥ 400 ng/ml and detection of EpCAM-positive CTC in peripheral blood prior to tumor resection as prognostic markers." (PMID 38012205, 2023). "Through PAM50 gene-set analysis, they effectively identified both minor and major tumor cell subgroups within the ALDH+/CD49f+/EpCAM+ population." (PMID 37830602, 2023). "Using EpCAM as a model antigen, we demonstrated that alanine scanning mutagenesis of the antibodies’ CDRs is an effective strategy to improve the tumor targeting specificity of CARs." (PMID 37045815, 2023). "The PanCK and EpCAM showed significant downregulation in Sel‐GemPac‐treated cancer cells of KPC mice tumour." (PMID 38131168, 2023). "In the present work, we performed an analysis of the expression of mesenchymal marker CD117 and cell adhesion glycoprotein EpCam in tumor cells and the abundance of these markers on the surface of tumor-derived extracellular vesicles." (PMID 36875773, 2023). "To define the mechanisms by which EMT tumour cells are resistant to chemotherapy, we assessed the expression of putative mediators of resistance to therapy in EPCAM+ and EPCAM− tumour cells from skin SCCs10,12." (PMID 36949199, 2023). "For this purpose, R11 ROR1-CAR-T cells were further transfected to express a synNotch receptor directed against a different tumor antigen (epithelial cell adhesion molecule (EpCAM) or B7-H3) expressed exclusively on ROR1+ tumor cells." (PMID 36873868, 2023). "The T1 and T2 tumor cells were also different in terms of the expression of epithelial markers (EpCam, E-Cadherin), mesenchymal markers (Vimentin, Pdgfra) and dormancy associated marker (Nr2f1) as shown by the qRT-PCR analysis." (PMID 37841442, 2023). "To generate tumor cell-selective agents that can degrade Ras, we created modular constructs that contain Ec1 for targeting EpCAM, the Ras-degrading enzyme RRSP as active cargo, and either the translocation domain from DT (RRSP-DT-Ec1) or ETA (Ec1-ETA-RRSP)." (PMID 37485031, 2023). "β-HIVS treatment decreased the population of EpCAM+ liver CSCs in a dose-dependent manner in vitro and suppressed tumor growth in vivo compared with the control vehicle." (PMID 38003473, 2023). "The proportions of non‐immune cells, primarily consisting of epithelial cell adhesion molecule+ (EpCAM+) epithelial cells, endothelial cells, and fibroblasts, increased sequentially from non‐tumor tissues to MIA and IA samples." (PMID 37991139, 2023). "Subsequently, tumour cells from the EpCAM-depleted fraction were again enriched with the CellSearch system, but this time EpCAM independently targeting Trop-2 and CD-49f." (PMID 36823365, 2023). "Immunohistochemically, tumor cells are positive for stem/progenitor cell markers, such as CK 19, EpCAM, cluster of differentiation 56 (CD56), CD117, and spalt-like transcription factor 4 (SALL4)." (PMID 37761023, 2023). "Napabucasin downregulates stemness-related genes Nanog, SOX2, Klf4, and Oct4 CD90 and EpCAM mRNA expression levels both in tumor cells and tumor tissues." (PMID 37570646, 2023). "EPCAM was utilized as a marker for circulating tumor cells, and roughly 30% of EPCAM+ cells were also PD-L1+." (PMID 37627156, 2023). "H&E, PROCR, and EpCAM staining of resected tumors revealed PROCR+ spindle-like tumor cells with pockets of PROCR+/EpCAM+ tumor cells." (PMID 37709737, 2023).
tumor (continued). "The frequency of CD47+ cells was higher within the double positive (EpCAM+CD24+) tumor cell population than in the EpCAM+CD24- tumor cell fraction in both the spheroids and the tumoroids." (PMID 37876933, 2023). "We found that, 12 h after cisplatin administration, 53BP1 nuclear foci were more abundant in EPCAM− tumour cells compared with in EPCAM+ and EPCAM−Rhoj-KD cells." (PMID 36949199, 2023). "In this study, EpCAM/vimentin/GPC3 antibody-modified LMS were used to capture tumor cells with epithelial phenotype, mesenchymal phenotype and GPC3 phenotype." (PMID 36681851, 2023). "Our previous work has shown that the aptamer against the epithelial cell adhesion molecule (EpCAM) exhibited tumor penetration capacity in xenograft tumor tissue that was at least four-fold of that of the EpCAM antibody due to the smaller size of aptamers." (PMID 36358973, 2022). "The three tumor-associated transcripts used here were MUC1 (mucin 1), HER2, and GA733-2—the messenger ribonucleic acid (mRNA) of the EpCAM." (PMID 35453519, 2022). "When healthy donor blood samples were spiked with variable amounts of different EpCAM+EGFR+ tumor cell lines, recovery yield was on average 75%." (PMID 36613466, 2022). "The expression of EpCAM was closely correlated with age (p = 0.029), Clinical T stage (p = 0.015), New tumor event after initial treatment (p = 0.037), and Prior malignancy diagnosis (p = 0.037)." (PMID 35517503, 2022). "CS consists of utilizing EpCAM in a first step to detect carcinoma cells in the blood, followed by a “purification” step in which all contaminating non-tumor cells (mainly white blood cells (WBCs)) are eliminated." (PMID 35482170, 2022). "Beyond its well-recognized role as a biomarker of cancer stem cells (CSCs) or circulating tumor cells (CTCs), EpCAM exhibits novel and promising value in targeted therapy." (PMID 36369033, 2022). "Most primary tumor cells maintained the expression of the epithelial markers EpCAM and ERα in our xenograft model while expressing ZEB1 and vimentin." (PMID 35440541, 2022). "CellSearch® (Menarini Silicon Biosystems, Inc., Huntington, PA, USA) is a platform that captures EpCAM-positive circulating tumor cells (CTCs) from whole blood samples." (PMID 36546899, 2022). "The tumor targeting properties of the engineered bacteria were evaluated in human embryonic kidney epithelial cells HEK293 transfected to overexpress EpCAM or HER2 receptors." (PMID 35155394, 2022). "To rigorously compare stemness traits in vivo, we sorted HCC38 cells into four populations based on their EpCAM and αvβ3 status prior to evaluating their tumor-initiating potential in vivo." (PMID 35027548, 2022). "CAR T cell trials targeting other tumor antigens including EpCAM and TGF-β in addition to GPC3 are underway." (PMID 35433430, 2022). "Epithelial cell adhesion molecule (EpCAM), a typical CAM, is highly associated with tumor proliferation and overexpressed in the majority of solid tumors, while being expressed at low levels in a variety of human epithelial tissues." (PMID 36431072, 2022). "CD45+EpCAM+ cells display the main tumor burden and more drug-resistance than EpCAM+ tumor cells in patients with NSCLC and EOC." (PMID 35711455, 2022). "In this report, we analyzed the expression of EpCAM in 33 different types of cancer through TCGA database, revealing the obvious difference of EpCAM expression between tumor and normal tissue in many cancers." (PMID 35517503, 2022). "Catumaxomab binds to EpCAM-overexpressed tumors and recruits T cells to tumor cells, which promote cytotoxic synapse formation and tumor cell lysis." (PMID 35735360, 2022).
tumor (continued). "In the 1970s, after administration of cancer cells to the mic, EpCAM was identified as a novel tumor-specific cell surface antigen." (PMID 35986321, 2022). "The engineered bacteria were tested for their ability to remove IL-8 and IL-6 from the supernatant of cancer cells and to bind tumor antigens EpCAM or HER2 on HEK293 cells." (PMID 35155394, 2022). "The main cell clusters included T cells (CD3E and CD3D), B cells (CD19), natural killer cells (NCAM1, FCGR3A and KLRD1), myeloid cells (CD86 and CD163) and tumor cells (EPCAM, KRT8 and KRT18)." (PMID 36497182, 2022). "EpCAM-specific ICE® constructs bound with a similarly high apparent affinity to EpCAM+ tumor cell lines and with the KD values ranging from 1.2 nM to 2.0 nM." (PMID 35225870, 2022). "In contrast, based on EpCAM activity on cell signaling pathways, its invasive functions in tumor growth and progression have been suggested in the bladder, gallbladder, breast, prostate, lung, pancreas, and renal cell carcinoma." (PMID 35016698, 2022). "The expression level of a tumor cell marker (EpCAM) can be directly determined in isolated CTCs at the single-cell level, and the therapeutic response to anticancer drugs can be simultaneously monitored." (PMID 35136652, 2022). "We then explored the comparison of tumor infiltration levels in PCa with different somatic copy number alterations for EpCAM." (PMID 35517503, 2022). "Ten of 10 human NSCLC samples showed ATRC-101 surface binding, with 35 to 90% of EpCAM+E-cadherin+ tumor cells showing positive staining." (PMID 35507878, 2022). "Even when HT29 cells in medium were enriched with EpCAM+ beads, yield was less than 40%, suggesting that 60–80% of tumor cells are lost during EpCAM enrichment, presumably due to retainment in the magnetic column." (PMID 36613466, 2022). "Under the external magnetic field, the magnetic particles of anti-EpCAM coating are fixed on the wavy HB surface to capture tumor cells." (PMID 35646880, 2022). "Detection of epithelial-derived cancers and circulating tumor cells historically has relied on the detection of both EpCAM and cytokeratin expression." (PMID 35976857, 2022). "Common epithelial and tumor markers were expressed to a variable extent: CD326 (EpCAM) (98.6% ± 1.7, MFI: 40.6 ± 3.1), CD227 (MUC-1) (58.4% ± 2.8, MFI: 7.8 ± 0.1), and CD66adecb (CEA) (38.2% ± 0.2, MFI: 5.0 ± 0.2)." (PMID 36761421, 2022). "DARPins specific formembrane-bound tumor markers (EpCAM, VEGF-A, HER2, as well as for themaltose-binding protein, MAP kinase, caspase 2, IgE antibody, and CD4) havebeen obtained." (PMID 35441046, 2022). "We used two tumour markers validated in the cell line-derived EVs: EpCAM, which has been described in EVs from epithelial cells and has been widely used as an epithelial cancer marker in blood (e.g., in Circulating Tumour Cells)." (PMID 35135541, 2022). "Ma-Mel-86c is positive for the tumour-associated immune ligand MICA while H3122 expresses the epithelial cell marker EpCAM." (PMID 35135541, 2022). "Tumor-specific antibodies (anti-EpCAM) were attached to the mat afterward to capture circulating tumor cells on the therapeutic system." (PMID 35683685, 2022). "CD24 and EpCAM on sEVs were highly overexpressed in phenotype analyses, providing an effective predictive tool for real-time noninvasive monitoring of tumor development in mice." (PMID 35281563, 2022). "EpCAM acts as a double-edged sword protein that has oncogenic and tumor suppressive behavior biologically." (PMID 35016698, 2022). "The authors show that EVs isolated from BrCa cell lines or OvCa ascites bound and sequestered tumour-reactive antibodies, such as the therapeutical anti-HER2 monoclonal antibody trastuzumab and an anti-EPCAM tumor-reactive antibody." (PMID 35563789, 2022). "They efficiently removed tumor cells that were added to healthy subjects’ blood samples, through an anti-EpCAM antibody interaction." (PMID 35890293, 2022).
tumor (continued). "Alternatively, platelets were pre-labeled with DiO cell tracker and the percentage of EpCAM+ tumor cells that acquired fluorescence is shown as platelets-educated tumor cells (PETs)." (PMID 35265204, 2022). "The folding of the DOS was aided by five pairs of DNA molecules containing SYL3C aptamer sequences that target epithelial cell adhesion molecule (EpCAM), a molecule specifically expressed on circulating tumor cells." (PMID 35208439, 2022). "Herein, we find that the expression of EpCAM, the widely used molecular marker for tumor cell characterization and isolation, is strongly upregulated in primary lung tumors, which is caused by both gene amplification and promoter hypomethylation." (PMID 36077658, 2022). "Circulating tumor cells express epithelial cell adhesion molecule (EpCAM) and/or cytokeratins (CK), stem cell-like markers, and lack panleukocyte marker CD45." (PMID 35207611, 2022). "This makes it possible to find higher numbers of EpCAM positive tumor cells at multiple points throughout the course of primary disease." (PMID 36661670, 2022). "ChiHEA125-Ama, conjugate of α-amanitin with a chimerized anti-EpCAM monoclonal antibody, exhibits tumor-suppressing potential in pancreatic, breast and various other cancers." (PMID 36369033, 2022). "When correcting for tumour size the analysis revealed a significantly higher expression of FAP in peritoneal metastases than in liver metastases (median FAP/EpCAM ratio was 1.7 for PM and 0.5 for CRLM, P value = 7.23e-06)." (PMID 35296803, 2022). "In summary, EpCAM×CD3 potently stimulates the secretion of effector cytokines by pre-activated lymphocytes in the presence of EpCAM-expressing tumor cells." (PMID 36132125, 2022). "In vivo, they accumulated into tumor masses in a mouse model of colon cancer, where immunostaining of tumor-extracted cells revealed an overexpression of EpCAM compared with cultured cells." (PMID 35626078, 2022). "ICE® constructs targeting the CD16A NK cell receptor induced a more extensive EpCAM+ tumor cell destruction than the EpCAM/NKp46 ICE®, despite a lower binding affinity to CD16A." (PMID 35225870, 2022). "Following cryopreservation, revived EpCAM/NKp46 ICE® and NK cell complexes were more potent activators of specific tumor cell lysis than the EpCAM/NKG2D ICE® complexes." (PMID 35225870, 2022). "EpCAM (+) OC cells have greater tumor-initiating potential compared to EpCAM (−) cells, and EpCAM expression is increased in chemo-resistant tumors and correlates with unfavorable outcomes." (PMID 36612107, 2022). "Protein transference analysis was observed on ImageStream experiments revealing that not only tumor cells are able to transfer a protein of epithelial origin (EpCAM) to platelets but also platelets transfer a private protein (CD42) to tumor cells." (PMID 35265204, 2022). "Several CD16A–BiKEs have been developed to target different tumor antigens, including the epithelial cell adhesion molecule (EpCAM), CD33, CD19, or CD20." (PMID 36231109, 2022). "In contrast to upregulation in primary lung tumors, EpCAM is severely repressed in metastatic lung tumors, which is mediated by promoter hypermethylation, histone deacetylation, and TGFβ from macrophage in tumor microenvironment." (PMID 36077658, 2022). "EpCAM plays critical roles in tumorigenesis to promote tumor cell proliferation, survival, and tumor-initiating potential." (PMID 35735360, 2022). "EpCAM has been reported to be involved in malignant proliferation, invasion, metastasis, and tumor recurrence." (PMID 36397165, 2022). "Hereafter freshly isolated CD44v6 (+)/EpCAM (+)/ALDH1 (+)/CD133 (+) cells from the corresponding sphere-propagated tumor cells will be referred to as CICs, and CD44v6 (–)/EpCAM (+)/ALDH1 (+)/CD133 (+) cells as Non-CICs." (PMID 36330477, 2022). "Malignant cells from fresh patients’ tumours were isolated by sorting for CD326(EPCAM) and placed in culture to generate tumour conditioned media." (PMID 34727230, 2022).